LINC01504 (long independently transcribed non-coding RNA 1504)
Gene: Long non-coding RNA gene on chromosome 9 (72,305,219 to 72,364,194, forward strand). Ensembl gene ENSG00000225434.
Diseases named in the same sentence as LINC01504 in open-access papers:
LINC01504 is named in the same sentence as 3 diseases in open-access papers, as found by Europe PMC text mining. Sharing a sentence is not in itself a finding about the gene and the disease. The quoted sentences say what the papers report.
non-small cell lung carcinoma (1 paper, 2022). A group of at least three distinct histological types of lung cancer, including non-small cell squamous cell carcinoma, adenocarcinoma, and large cell carcinoma. "Increased levels of LINC01504 in the non-small cell lung cancers cell lines A549, NCI-H1650, SK-MES-1 and NCI-H226 exposed to cinnamaldehyde promoted the production of cytokine signaling 1 (SOCS1), BTG anti-proliferation factor 2 (BTG2), and Bruton tyrosine kinase (BTK)." (PMID 36499073, 2022).
sarcoma (1 paper, 2020). A usually aggressive malignant neoplasm of the soft tissue or bone. "Among the identified three-lncRNA signature, LINC01504 is involved in nontranslocation-related sarcomas." (PMID 33633568, 2020).
LINC01504 also shares sentences with these, for which no sentence is quoted: asthma (1 paper).